MDM2 (MDM2 proto-oncogene)
Diseases named in the same sentence as MDM2 in open-access papers (continued):
Sharing a sentence is not in itself a finding about the gene and the disease.
ovarian carcinoma (continued). "An in-vitro study conducted on a human ovarian cancer cell line (SKOV3) demonstrated the role of MDM2 in promoting EMT through inhibition of E-cadherin and activation of various growth-promoting transcription factors e.g., TGF-β/Smads and Snail/Slug." (PMID 37314603, 2023). "MiR-646 currently seems involved in cell proliferation and metastasis in a variety of tumors and was reported to mediate the VAMP2 and MDM2 genes at the post-transcriptional regulation level, thereby inhibiting the activity of ovarian cancer cells." (PMID 35022405, 2022). "The observed increase in MDM2 expression was lower for exosomes derived from α-mangostin and/or cisplatin-treated ovarian cancer cells." (PMID 36012171, 2022). "There are also other reports indicating that miR-194-5p induces p21 upregulation and G1 phase arrest in drug-resistant cells by downregulating MDM2, thereby resensitizing drug-resistant ovarian cancer cells to paclitaxel." (PMID 34127010, 2021). "This SNP285 counteracts the increased affinity of SP1 for the MDM2 promotor and has been observed in breast and ovarian cancers." (PMID 34065345, 2021). "In our study, combination of MDM2 inhibitor AMG-232 with anti-PD-1 treatment (pembrolizumab) enhanced T-cell-mediated tumor killing in the OVMANA ovarian cancer cell line." (PMID 32655895, 2020). "We found that high MDM2-expressing ovarian cancer cell lines are more resistant to T-cell-mediated killing and can be sensitized through targeting MDM2 by siRNA or pharmacological inhibition with AMG-232." (PMID 32655895, 2020). "In conclusion, in this study, we found that miR-194-5p loss is deeply involved in acquired resistance to paclitaxel and restoring miR-194-5p expression attenuates paclitaxel resistance by targeting MDM2 in ovarian cancer cells." (PMID 30774764, 2019).
ovarian carcinoma (continued). "In the context of ovarian cancer it is of interest to investigate the combination of cisplatin and MDM2 inhibitors, particularly as individually these agents have different dose limiting toxicities." (PMID 27223080, 2016). "MDM2 expression in ovarian cancer tissues was analyzed by microarray and real-time PCR, and its relationship with prognosis was evaluated by Kaplan-Meier method and log-rank test." (PMID 27659536, 2016). "So it is worthy to make a meta-analysis to evaluate relationship between MDM2 SNP309 polymorphism and ovarian cancer." (PMID 23383041, 2013). "At last, six studies on MDM2 SNP309 genotypes and ovarian cancer risk were identified, including a total of 1534 ovarian cancer cases and 2211 controls." (PMID 23383041, 2013). "Here we report the distribution of the MDM2 SNP285G>C and SNP309T>G polymorphisms in 221 Norwegian ovarian cancer patients diagnosed with germline mutations in BRCA1 (n = 161) and BRCA2 (n = 60)." (PMID 23039163, 2012). "In conclusion, we found the MDM2 SNP309 to increase and SNP285C to reduce the risk of ovarian cancer in BRCA1 related ovarian cancer." (PMID 23039163, 2012). "We explored the distribution of the MDM2 polymorphisms SNP309T>G and the recently discovered SNP285G>C in Norwegian patients with BRCA related ovarian cancer." (PMID 23039163, 2012). "We tested 1371 breast and 179 ovarian tumours by Southern blotting and observed amplification of 20q13 in 5.4% breast and 2.8% ovarian carcinomas, whereas MDM2 was found amplified in 5.3% and 3.8% of breast and ovarian tumours respectively." (PMID 8980401, 1996). "In addition, high resistance in MDM2 over-expressive ovarian cancer cell lines has been observed against T-cell mediated death whereas silencing MDM2 results in enhanced sensitivity." (PMID 37314603, 2023). "hMOF/MDM2 axis might be a potential target for the treatment of chemotherapy-resistant ovarian cancer." (PMID 37291112, 2023).
ovarian carcinoma (continued). "Meta-analysis of the association between MDM2 SNP309 polymorphism and ovarian cancer risk." (PMID 23383041, 2013). "In ovarian cancer expression, MDM2 is more characteristic of serous LMP." (PMID 16421595, 2006). "Previous evidence indicates that the RING-domain E3 ubiquitin ligases including Cullin-RING E3 ligase complexes such as SCF complex (SKP1, Cullin and F-box protein), the APC/C complex, as well as monomeric XIAP, MDM2, MUL-1, Pirh2, and SIAH2 may all be associated with ovarian cancer chemoresistance." (PMID 35582023, 2021). "This meta-analysis provides evidence for the association between MDM2 309 polymorphism and ovarian cancer risk, supporting the hypothesis that MDM2 SNP309 G allele acts as an important ovarian cancer protective factor in Asians but not in Caucasians." (PMID 23383041, 2013). "AMG232 is an investigational orally bioavailable selective MDM2 inhibitor, and the combination of AMG232 and pembrolizumab anti-PD-1 treatment reduces IL-6 expression as well as enhances T cell-mediated tumor killing in ovarian cancer cell lines." (PMID 39253578, 2024). "Collectively, the results of the study confirm that MDM2 as a novel non-histone substrate of hMOF, participates in promoting hMOF-modulated cisplatin chemoresistance in ovarian cancer cells." (PMID 37291112, 2023). "In addition, the microarray study has detected aberrant AS of genes in ovarian carcinomas, including FGFR2, DNNP3B, KITLG, MDM2 and MRP123." (PMID 34001978, 2021).
ovarian carcinoma (continued). "We also demonstrated that the Ras /ER/MDM2 pathway was critical for NIH3T3 cell line transformation and the blockage of this pathway resulted in an inhibitory effect in estrogen-depended gynecological cancers such as ovarian cancer and endometrial cancer." (PMID 26293665, 2015). "No observable link was established between MDM2 SNP309 and ovarian cancer susceptibility of Caucasian women in two case-control studies." (PMID 23383041, 2013). "Two studies were not focused on MDM2 SNP309T/G polymorphism and ovarian cancer risk." (PMID 23383041, 2013). "Thus nearly 10% of ovarian cancer patients (one third of the 30% not high grade serous) who are likely to be sensitive to both MDM2 inhibitors and rucaparib may benefit from combination treatment with these agents." (PMID 29050241, 2017).
lipoma (62 papers, 2000 to 2026). A benign, usually painless, well-circumscribed lipomatous tumor composed of adipose tissue. "Extrapolating from these criteria, we propose performing MDM2 FISH testing on atypical spermatic cord lipomas greater than 10 cm to avoid potential diagnostic pitfalls." (PMID 40799874, 2025). "•Critical Diagnostic Challenges:Mimics benign lipomas; MDM2/CPM testing (100% sensitivity/specificity) and red flags (age > 50, rapid growth, deep location) are critical." (PMID 40674962, 2025). "An important gene associated with invasive lipoma is MDM2 (MDM2 Proto-Oncogene)." (PMID 37492162, 2023). "Summary of patient’s demographics including age, specimen laterality, size of the spermatic cord lipoma cases, and MDM2 FISH amplification status." (PMID 40799874, 2025). "Overall, 170 cases were classified as lipomas and 55 as atypical lipomatous tumours; in all but one of the latter, MDM2 amplification was confirmed." (PMID 41464192, 2025). "A total of 101 patients had a lipoma, and 18 tumours were classified as atypical lipomatous tumours (all with confirmed MDM2 amplification)." (PMID 41464192, 2025). "More studies with increased sample size are necessary to be able to reach definitive cutoff criteria for MDM2 FISH testing on spermatic cord lipomas with atypical features." (PMID 40799874, 2025). "Fluorescence in situ hybridization (FISH) for MDM2 gene amplification would be the gold standard test in such cases to help determine the nature of such atypical spermatic cord lipomas." (PMID 40799874, 2025). "By definition, MDM2 amplification exhibits a very high predictive value in distinguishing ALTs from lipomas." (PMID 40564858, 2025). "Differentiating atypical lipomatous tumors (ALTs) from lipomas using imaging techniques is a challenge, and the biopsy with immunohistochemical determination of murine double minute 2 (MDM2) oncogene is the gold standard." (PMID 39997549, 2025). "In summary, our series provides another cohort confirming the presence of lipomas in the retroperitoneum, which were diagnosed prospectively with the help of MDM2 FISH." (PMID 37131332, 2024). "In conclusion, radiogenomic models were developed that showed a high discriminatory power for predicting the MDM2 gene amplification status to distinguish between atypical lipomatous tumors and lipomas on preoperative MR images." (PMID 37046811, 2023). "The safest discrimination between an ALT and a lipoma can be achieved by immunohistochemistry against the proteins of the MDM2 and CDK4 genes." (PMID 35626435, 2022). "We evaluated and compared cytological findings, MDM2 amplification, and histological diagnosis to identify patient samples either as lipomas or ALTs/WDLs." (PMID 34984861, 2022). "MDM2 FISH test is needed in adjunct to histology to distinguish between lipoma and atypical lipomatous tumor." (PMID 34348760, 2021). "We retrospectively collected 49 patients with lipomas or WDLs utilizing MDM2 for pathologic diagnosis." (PMID 29755284, 2018). "Our experience of FISH for testing MDM2 amplification shows high concordance in established histological diagnoses of lipoma and WDL/DDL." (PMID 25810689, 2015). "A series of lipoma (n = 124) and ALT/WDL (n = 44) cases were analyzed for cytogenetic analysis and lipoma fusion genes, as well as for MDM2 and CDK4 expression by real-time PCR." (PMID 24965044, 2014). "The medians for MDM2 relative expression levels were 2.0 (range, 0.2–54.1) for lipoma and 3.4 (range, 0.4–52.5) for ALT/WDL." (PMID 24965044, 2014). "The medians for relative MDM2 expression were 1.3 (range, 0.1–28.2) for lipoma and 3.9 (range, 0.4–21.6) for ALT/WDL." (PMID 24965044, 2014). "In this retrospective study, we describe the clinicopathologic features and provide follow-up information on 9 abdominal and retroperitoneal lipomas that we diagnosed since 2009 with the help of fluorescence in situ hybridization (FISH) assay for MDM2 amplification." (PMID 37131332, 2024).